INS (insulin)
Diseases named in the same sentence as INS in open-access papers (continued):
Sharing a sentence is not in itself a finding about the gene and the disease.
Hypoglycemia (continued). "Reducing insulin doses during dialysis sessions, considering the absence of typical symptoms of hypoglycaemia and providing patients with snacks before meals are crucial considerations in optimizing glycaemic control and minimizing adverse events in this patient population." (PMID 41536569, 2026). "It was proposed that this effect may not be due to insulin itself, but rather to the rapid hypoglycemia it induces; however, on the other hand, certain insulin types such as lispro and glargine have been specifically linked to the progression of DR." (PMID 40510890, 2025). "However, in vivo, pilots using CSII in-flight did not experience a fall in blood glucose or episodes of hypoglycaemia during these atmospheric pressure changes and the use of insulin pumps can be endorsed in view of their clinical benefits." (PMID 39496965, 2025). "Synthetic SGLT2 inhibitors lower glucose primarily through promoting glucosuria, and in this way, these molecules are effective at lowering plasma glucose concentrations without inducing hypoglycemia because they act independently of the need for the pancreas to secrete or respond to insulin." (PMID 40872492, 2025). "However, excessive insulin secretion can result in life-threatening hypoglycemia, which is often misdiagnosed due to its nonspecific early symptoms, leading to a delayed diagnosis." (PMID 39968426, 2025). "Therefore, it is crucial for healthcare personnel to understand the risks of hypoglycemia that could occur in the pediatric population when engaging in VPA, particularly if insulin dosage exceeds recommended levels." (PMID 38954647, 2025). "Therefore, hyperinsulinemia is often clinically defined by elevated fasting insulin relative to average levels for a particular age and health status, without hypoglycemia." (PMID 40013621, 2025). "The administration of NPH insulin every 8 h as opposed to every 12 h was anticipated to dampen peak and nadir insulin concentrations, thereby potentially reducing glycemic variability and the occurrence of hypoglycemia." (PMID 40944267, 2025). "Thus, early utilization of 10% dextrose may be warranted for managing SGLT2i DKA to enable higher insulin doses and prompt DKA resolution, with the theoretical benefit of less hypoglycemia." (PMID 40843859, 2025). "Unlike sulfonylureas, which stimulate insulin secretion independently of blood glucose and can lead to hypoglycemia, GLP-1RAs improve glycemic control in a glucose-dependent manner, thereby minimizing the risk of hypoglycemia." (PMID 40708853, 2025). "Consequently, insulin and IGF-1 are typically low during the profound hypoglycemia episodes." (PMID 41209155, 2025). "Such guidance could allow for remission to achieved quickly without giving too high an insulin dose (risking hypoglycemia) or excessive (costly) doctor–patient interactions." (PMID 38895272, 2025). "This might have been because the intervention focused on preventing hypoglycemia and stabilizing fasting blood glucose, without placing enough emphasis on detailed management of postprandial carbohydrate intake, insulin dosage, and post-meal activities." (PMID 41346986, 2025). "Hypoglycemia is rare, particularly in patients not receiving insulin or sulfonylureas." (PMID 39917155, 2025). "Detection limitations in conventional insulin immunoassays may wrongly suggest non-insulin-mediated hypoglycemia." (PMID 39030378, 2025). "Although dynamic insulin testing was not performed, our case supports that a preserved insulin reserve under catecholaminergic suppression may manifest as severe hypoglycemia once suppression is removed." (PMID 40726849, 2025). "However, the co-administration of GLP-1RA with insulin or sulfonylurea is not advisable to avoid the incidence of hypoglycemia." (PMID 40861717, 2025). "When tirzepatide is used without insulin, the incidence of hypoglycemia remains low." (PMID 40607140, 2025).
Hypoglycemia (continued). "The lack of educational resources about U200-AID may complicate education for both PWD and HCPs, which could in turn lead to errors in programmed insulin delivery settings that may lead to a two-fold over- or under-dose of insulin and result in adverse events such as DKA or hypoglycemia." (PMID 41230085, 2025). "Advanced automated insulin delivery and glucose monitoring systems may help reduce some, but not all, hypoglycaemia – and do not necessarily alleviate fear of hypoglycaemia." (PMID 40688059, 2025). "Fall/fracture event rates were numerically higher for people with vs without hypoglycemia, regardless of whether participants were newly initiating basal insulin or switching basal insulin." (PMID 40309264, 2025). "People with vs without hypoglycemia experienced more falls/fractures, regardless of whether initiating basal insulin or switching basal insulin treatment." (PMID 40309264, 2025). "Her pump downloads from May 2023 and January 2024 did not demonstrate a change in time in range (TIR) but she had a decrease in her total insulin dose, with no increase in severe episodes of hypoglycemia, with continued maintenance of good glycemic control." (PMID 39707844, 2025). "The diminished insulin and C-peptide levels, together with the patient's medication history and the lack of pertinent autoimmunity, ruled out insulinoma, factitious hypoglycemia from exogenous insulin or sulfonylureas, autoimmune hypoglycemia, and adrenal insufficiency." (PMID 41333493, 2025). "The availability of FRCs of basal insulin (BI) and GLP‐1RAs offers a simplified option to advance therapy in T2DM to further improve glycaemic control, lower body weight without increasing, even lowering, the risk of hypoglycaemia." (PMID 40678871, 2025). "For example, if a patient experiences hypoglycemia once a month, this may be considered normal for an older adult using insulin and may not necessitate an educational intervention." (PMID 40361775, 2025). "As the first meta-analysis investigating the effect of intranasal insulin on postoperative delirium (POD) in adult surgical patients, this study demonstrates that intranasal insulin significantly reduces POD incidence, promotes cognitive recovery, and does not increase hypoglycemia risk." (PMID 41312480, 2025). "Dietary carbohydrate restriction can promote weight loss and improve blood glucose control, but Veterans taking certain medications (eg, insulin) may experience serious complications (eg, hypoglycemia) without adequate support and monitoring." (PMID 41397294, 2025). "Magel2-null mice had elevated basal corticosterone levels, and although male Magel2-null mice had an intact corticosterone response to restraint and to insulin-induced hypoglycemia, female Magel2-null mice failed to respond to hypoglycemia with increased corticosterone." (PMID 41516228, 2025). "Additionally, results show that once-weekly insulin are effective in managing blood glucose levels with no significant increase in hypoglycemia." (PMID 39810242, 2025). "Where insulin is required, GLP-1 RA + basal insulin (free combination) or fixed-ratio combinations (insulin glargine/lixisenatide; insulin degludec/liraglutide) can improve glycemia with less weight gain and without increasing hypoglycemia versus basal insulin alone." (PMID 41299307, 2025). "Errors in insulin pump management can potentially result in severe hypoglycaemia, hyperglycaemia or DKA that may not be caught by typical hospital safeguards, such as pharmacy review or scheduled point‐of‐care testing." (PMID 39432570, 2025). "This may be explained by satisfaction with the relief in everyday life after the procedure, without the need for constant insulin injections, blood glucose monitoring, and fear of the consequences of hypoglycemia." (PMID 41227173, 2025).
Hypoglycemia (continued). "Such guidance could allow for remission to be achieved quickly without giving too high an insulin dose (risking hypoglycemia) or excessive (costly) doctor–patient interactions." (PMID 40662943, 2025). "The purpose of this note is to emphasise the importance of including tests for antibodies, eg polyethylene glycol (PEG), in the early investigations of hypoglycaemia of unknown origin, in non-diabetic patients without previous exposure to insulin." (PMID 41349642, 2025). "GLP-1 RAs mimic the function of natural GLP-1 by enhancing insulin secretion in response to glucose and inhibiting excessive glucagon secretion, leading to a decrease in HbA1c, FPG, and postprandial glucose excursions, all without the risk of hypoglycemia." (PMID 41007868, 2025). "Persons on MDI regimens may experience barriers which affect their insulin adherence and glycemic control, such as fear of hypoglycemia, lack of adequate injection instructions, medication regimen complexity, among others." (PMID 40142601, 2025). "By contrast, the continuous intravenous infusion of glibenclamide to patients with large hemispheric ischemic infarctions provided a constant therapeutic dose of the agent without spikes in serum drug levels leading to insulin release and resultant hypoglycemia." (PMID 40722270, 2025). "Previous studies have shown that combining insulin therapy with SGLT2 inhibitors in outpatients does not increase the risk and may reduce nocturnal hypoglycemia." (PMID 40828947, 2025). "People in hospital with metabolic stress may be started on insulin, or have their doses ramped up several fold, only for this to result in hypoglycaemia if not properly managed after discharge." (PMID 40035222, 2025). "Individuals with recent myocardial infarction, impaired renal function, diabetic ulcers, a limited capacity for physical activity, insulin onset (<6 months), recurrent or severe hypoglycemia, a high baseline for physical activity, or no internet access were excluded." (PMID 41595846, 2025). "Our results suggest intranasal insulin may protect perioperative cognitive function, reduce POD incidence, mitigate postoperative inflammation, and does not increase hypoglycemia risk." (PMID 41312480, 2025). "The mechanism of hypoglycemia secondary to dasatinib is not well described, but as seen in this case, it may be due to an insulin-mediated process." (PMID 39659385, 2024). "Moreover, factors significantly influencing hypoglycemia were high HbA1c (uncontrolled blood glucose), no smoking habit, a physically active lifestyle, comorbidities, and insulin/sulfonylurea users." (PMID 38243951, 2024). "The rate of patients that achieved an HbA1c <7.0% without developing clinically significant or severe hypoglycemia events at week 52 were significantly lower in patients receiving insulin icodec rather than the control (7.2% vs. 11.6%; estimated odds ratio = 0.59; 95%CI: 0.37 to 0.95)." (PMID 38610878, 2024). "The incidence of hypoglycemia after MVR was 14.2%, and plasma glucagon concentrations increased in these dogs (mean: 260 pg/mL and 644 pg/mL pre- and postoperatively, p < 0.001), whereas serum insulin concentrations decreased (median: 0.50 ng/mL and 0.29 ng/mL pre- and postoperatively, p = 0.002)." (PMID 38393097, 2024). "The rate of patients that achieved an HbA1c < 7.0% without developing clinically significant or severe hypoglycemia events at week 52 were significantly higher in patients receiving insulin icodec rather than the control (41% vs. 32%; estimated odds ratio = 1.47; 95%CI: 1.13 to 1.92)." (PMID 38610878, 2024). "Switch from BID basel insulin to OD Gla-300 as part of basal bolus therapy in T1D resulted in similar glycemic control as measured by HbA1c, but provided significant improvements in SMBG, daily glucose profile, a lower incidence of hypoglycemia and increased patient satisfaction." (PMID 38982528, 2024).
Hypoglycemia (continued). "Increased insulin action can be demonstrated by increased glucose requirement (e.g., >8 mg/kg/min in a neonate normal 4–6 mg/kg/mi), inappropriately suppressed plasma concentrations of FFA and BOHB during hypoglycemia, and an inappropriate glycemic response to glucagon at a time of hypoglycemia." (PMID 37454648, 2024). "Additionally, children with positive tests had a significantly higher insulin dose, more hypoglycemia attacks, and recurrent DKA compared to negative cases." (PMID 38317100, 2024). "Critically, the use of a basal insulin allows for meals to be skipped without risking hypoglycemia." (PMID 38831362, 2024). "The lack of variation in hypoglycemia awareness between patients who used different types of insulin suggests that the choice of insulin treatment may not be a decisive factor in predicting awareness levels." (PMID 39539431, 2024). "Thus, aggravated insulin-induced hypoglycemia in Trpc5 KO animals is not paralleled by up- or downregulated secretion of corticosterone in the plasma." (PMID 39375537, 2024). "Switch from BID basal insulin to OD Gla-300 as part of basal bolus therapy in T1D resulted in similar glycemic control as measured by HbA1c, but provided significant improvements in SMBG, daily glucose profile, a lower incidence of hypoglycemia and increased patient satisfaction." (PMID 38982528, 2024). "Similarly, our study showed that the risk of hypoglycemia was not different among the GLP-RAs and insulin users at dialysis commencement." (PMID 39080745, 2024). "After 6 months, similar improvements in HbA1c were reported in both those who were switched to an FRC or to basal insulin with a gliflozin compared to those managed with a basal-bolus regimen, with the added benefit of fewer daily injections, less hypoglycemia, and no weight gain." (PMID 37787888, 2024). "Secondly, the doctor’s attitude regarding when to start insulin, or his/her clinical experience and competence with tackling key challenges related to insulin treatment, such as technical operation of insulin pens, hypoglycemia, weight gain and/or nonadherence, are also factors to consider." (PMID 38116986, 2024). "The inability to secrete glucagon normally when exposed to hypoglycemia in T1D may be because of intra-islet dysregulation in the absence of insulin secretion from pancreatic ß-cells and/or elevated somatostatin (SST) signalling from nearby pancreatic δ-cells." (PMID 38510652, 2024). "Moreover, the Vhl cKO female mice exhibited hypoglycemia and no changes in serum insulin levels or basal glucose clearance ability." (PMID 38945950, 2024). "However, the intranasal administration of insulin, which allows a more direct access to the cerebrospinal fluid than systemic or intraperitoneal application, did not provoke hypoglycemia." (PMID 39375537, 2024). "For patients who wear insulin pumps or those who require multiple daily insulin injections, hypoglycemia prediction based on CGM data could provide a timely warning of impending hypoglycemia for the individual to take immediate action and increase their glucose levels." (PMID 38801705, 2024). "These mice were not fasted to avoid hypoglycemia with acute insulin treatment." (PMID 39316677, 2024). "However, this is a crude or simple cost-change calculation for three months of use of insulin and not an extensive cost analysis, and costs for hospitalisation due to hypoglycaemia and T2DM-related complications were not included in this study." (PMID 38694591, 2024). "Fear of hypoglycemia is also frequently present among parents of young children with T1D due to glycemic variations, related to many variables, such as carbohydrate ingestion, lack of insulin, psychical activity, and others." (PMID 39680256, 2024).
Hypoglycemia (continued). "However, despite new technologies and therapies that target hyperglycemia, such as new oral agents (including GLP-1 analogs), new insulin and continuous glucose monitors (CGM), hypoglycemia remains a major barrier to tight glycemic control, even in patients with type 2 diabetes (T2D)." (PMID 38510652, 2024). "Interestingly, avexitide, a GLP-1 antagonist, reduced postprandial insulin secretion and subsequent hypoglycemia in PBH, but this is not yet approved by the USA Food and Drug Administration." (PMID 39444516, 2024). "The apparent dichotomy of these insulin effects may be explained by the effect of insulin on glucose production—insulin induces hypoglycemia which in turn increases appetite rather than via a direct effect of insulin in itself." (PMID 38019584, 2024). "Notably, a significant number of mice receiving the Fc-modified insulin without lipid experienced hypoglycemia (hunched posture, lethargy, BG was lower than 30 mg dL−1) and subsequently required intervention, or exclusion from the study." (PMID 39092439, 2024). "Earlier investigations showed that β-adrenoceptor blockade counter regulates decreased plasma glucose concentration after insulin-induced hypoglycemia but does not interfere with other hormonal (e.g., cortisol, glucagon, and growth hormone) responses to hypoglycemia." (PMID 39640497, 2024). "However, clinically significant (level 2) or severe (level 3) hypoglycemia was not significantly different in the once-weekly insulin group compared with once-daily insulin (OR 1.19; 95% CI 0.93 to 1.53; I2 = 53%; p = 0.16)." (PMID 39629047, 2024). "Therefore, it is possible that the substance P expressed in response to insulin-induced hypoglycaemia is indeed not released from the adrenal gland." (PMID 38392992, 2024). "The combination of its glucose-responsive behavior and protection against hypoglycemia suggests that NNC2215 could lead to more aggressive insulin titration without the fear of dangerously low glycemia." (PMID 39766270, 2024). "A similar 2016 clinical study in Argentina, where 8 patients underwent intraperitoneal transplantation with encapsulated neonatal porcine islets, also saw patients experiencing fewer episodes of unaware hypoglycemia and an improvement in HbA1c, but no change in daily insulin injections." (PMID 39553396, 2024). "Net budget impact from insulin costs with and without the cost of severe hypoglycemia." (PMID 39877917, 2024). "Although the incidence of severe hypoglycemia was not statistically significant in the insulin glargine group, the faster reduction in blood sugar levels resulted in a decrease in the continuous short-acting insulin dose." (PMID 40433420, 2024). "Similarly, FOXA2 controls insulin secretion; however, FOXA1 and FOXA2 have opposing effects on insulin regulation, and the absence of FOXA2 leads to increased insulin secretion and induces hypoglycemia." (PMID 38605023, 2024). "Fasting hypoglycemia or insulin-induced hypoglycemia was not able to ameliorate brain injury." (PMID 38235171, 2024). "With automated mode and hypoglycemia, it is important not to overtreat with CHO as this may cause the pump to increase the insulin delivery too much, causing recurrent episodes of hypoglycemia." (PMID 38785359, 2024). "The rate of patients that achieved an HbA1c <7.0% without developing clinically significant or severe hypoglycemia events at week 26 were significantly higher in patients receiving insulin icodec rather than the control (37% vs. 27%; estimated odds ratio = 1.59; 95%CI: 1.07 to 2.36)." (PMID 38610878, 2024). "Furthermore, patients reporting symptomatic (P = 0.048) but not severe (P = 0.96) hypoglycemia were fewer with long- vs. short-acting GLP-1 RA added to insulin." (PMID 37468901, 2023). "Among the 21 patients who did not receive insulin or secretagogues during their stay, only 2 developed mild hypoglycemia (which, therefore, could be considered spontaneous hypoglycemia)." (PMID 38044455, 2023).